RNA5SP535 (RNA, 5S ribosomal pseudogene 535)
Gene: Ribosomal RNA gene on chromosome 11 (102,057,854 to 102,057,960, forward strand). Ensembl gene ENSG00000274097.
Homologues: Orthologues: chimpanzee 5S_rRNA (52% identical), chimpanzee 5S_rRNA (51% identical), mouse Gm54527 (51% identical), chimpanzee 5S_rRNA (50% identical). Paralogues in human: RNA5SP172 (55% identical), RNA5SP443 (55% identical), RNA5S1 (54% identical), RNA5S10 (54% identical), RNA5S11 (54% identical), RNA5S12 (54% identical), RNA5S13 (54% identical), RNA5S14 (54% identical), RNA5S15 (54% identical), RNA5S16 (54% identical), RNA5S17 (54% identical), RNA5S2 (54% identical), and 26 more.